CHD7 (chromodomain helicase DNA binding protein 7)
Diseases named in the same sentence as CHD7 in open-access papers (continued):
Sharing a sentence is not in itself a finding about the gene and the disease.
cancer (22 papers, 2008 to 2025). A tumor composed of atypical neoplastic, often pleomorphic cells that invade other tissues. "Chd7 is implicated in a number of developmental disorder and is reported to play a role in cancer as well." (PMID 30735509, 2019). "Chd7 is implicated in a number of developmental disorder and is interestingly dysregulated in spectrum of cancer subtypes with aberrant expression, copy number variation, and somatic mutations." (PMID 30735509, 2019). "Much work is needed to decipher the biological impacts and underlying mechanisms of these CHD7 mutations on cancer pathogenesis." (PMID 28649742, 2017). "In this study, we revealed that in human cancer most CHD7 mutations are missense, and those mutations were distributed throughout the entire coding region of the CHD7 gene." (PMID 28649742, 2017). "Our findings suggest that CHD7 CRA_e is a functionally significant alternative transcript and not an aberrant transcript or splice event associated with a specific cell line or cancer cells." (PMID 20925924, 2010). "Moreover, CHD7 has been described to be essential for neural stem cells and it is also highly expressed or mutated in a number of human cancers." (PMID 30850678, 2019). "Thus, our results demonstrate the oncogenic potential of CHD7 and its association with poor prognostic parameters in human cancer." (PMID 28649742, 2017). "Here, we analyzed the mutation spectra of CHD6 and CHD7 genes in human cancers." (PMID 28649742, 2017). "Recent studies have highlighted the involvement of CHD7 in the transcriptional regulation of cancer-associated genes, with evidence suggesting that its dysregulation may contribute to altered chromatin architecture and oncogenic signaling in advanced prostate malignancies." (PMID 40491606, 2025). "When focusing on the CS‐scores of ATPCRs in individual cancer types, we observed that the maximum CS‐score corresponded to CHD7 in CRC (CS‐score = 4)." (PMID 35789070, 2022). "Eventually, seven ATPCR encoding genes, including ATRX, CHD5, CHD7, SMARCA4, SMARCA2, EP400, and ACTB, were identified as driver genes by at least two algorithms in certain cancer types." (PMID 35789070, 2022). "We identified 15 recurrent fusion gene pairs among all cancer types, with CHD7‐TOX (n = 4), EP400‐SFSWAP (n = 4), and SMARCA4‐DNM2 (n = 4) having the highest frequencies." (PMID 35789070, 2022). "This will pave the way to the proposal of novel therapeutic strategies aimed at bypassing CHD7 dysregulation, both in developmental syndromes and cancer." (PMID 33869187, 2021). "Recently, a few efforts tried to dissect how CHD7 expression or deregulation in CNS- and NC-derived cancers affects tumorigenesis." (PMID 33869187, 2021). "In this article, we will review the latest insights on CHD7 and semaphorins interactions during embryonic development, developmental disorders, and cancer progression, with a particular focus on neural crest (NC) and neuronal systems." (PMID 33869187, 2021). "The expression of BRG1 engages in pre-mRNA splicing through interacting RNPs in cancers; however, the detailed molecular pathology of how BRG1and CHD7 relate to cancer development remains largely unveiled." (PMID 32071290, 2020). "We found that CHD6 and CHD7 were the most commonly gained/amplified or mutated, whereas CHD1 and CHD3 were the most deleted CHDs in a spectrum of human cancers." (PMID 28649742, 2017). "Our findings provide a strong foundation for further mechanistic research and for developing therapies that target CHD7 or other CHDs in human cancer." (PMID 28649742, 2017). "We found that CHD6 and CHD7 were most commonly gained/amplified or mutated, whereas CHD1 and CHD3 were most deleted in a spectrum of human cancers." (PMID 28649742, 2017). "Integrated genomic, transcriptomic, clinicopathological data, and in vitro siRNA‐mediated knockdown assays revealed the oncogenic potential of CHD7 in multiple cancer types, notably those arising from breast." (PMID 28649742, 2017).
cancer (continued). "CHD7 also showed an increased copy number and an overexpression in 13 and 9 cancer types, respectively, suggesting its oncogenic roles in multiple types of cancer." (PMID 35789070, 2022). "Furthermore, a recent large-scale genomic analysis of human cancers confirmed the dysregulation of CHD7 in many malignancies, including breast, lung, colorectal, and ovarian cancers." (PMID 33869187, 2021). "With similar mechanisms, in adults, CHD7 controls the expression of gene sets involved in stemness maintenance during homeostasis as well as in invasiveness and angiogenesis during cancer progression." (PMID 33869187, 2021). "In many forms of cancers, deregulation of CHD7 expression promotes oncogenesis." (PMID 33869187, 2021). "In addition, a number of studies reported frequent mutations in human cancers: CHD6 in bladder cancer, CHD7 in medulloblastoma, whereas CHD8 harbors mutations in many cancer types." (PMID 32453735, 2020). "The expression of BRG1 engages in pre-mRNA splicing through interacting RNPs in cancers;3–5 however, the detailed molecular pathology of how BRG1and CHD7 relate to cancer development remains largely unknown." (PMID 32071290, 2020). "In addition to similar phenotypes of CHD7 and MLL4 mutations on human development, both CHD7 and MLL3/4 complex components are mutated in cancers." (PMID 31112698, 2019). "We propose that PKM2 abrogates the Chd7 mediated remodeling activity and thereby may exacerbate the genomic integrity and further contribute to cancer initiation and progression." (PMID 30735509, 2019). "Notably, CHD7 physically interacted with SRY‐box 2 (SOX2) transcriptional factor and regulated a set of common target genes associated with cancer and developmental disorders." (PMID 28649742, 2017). "A notable finding from our study is the dysregulation of CHD7 in a subset of human cancers." (PMID 28649742, 2017). "In addition, there is no information yet on CHD7 protein domain-specific functions, over-expression phenotypes, or potential roles for CHD7 in cancer or aging." (PMID 20657659, 2010). "Altogether, further knowledge on the CHD7 isoforms (including CHD7 CRA_e) and their biological roles should significantly impact our current understanding of several diseases, including developmental disorders and cancer." (PMID 20925924, 2010). "Thus, CHD7 likely modulates expression of a set of genes that are critical for cancer pathogenesis." (PMID 28649742, 2017). "Especially, 7 of ATPCRs showed a significant overexpression in multiple cancer types, including TTF2 (n = 6), RAD54L (n = 4), ACTL6A (n = 4), CHD7 (n = 3), HELLS (n = 3), HLTF (n = 3), and ACTR5 (n = 3)." (PMID 35789070, 2022). "In summary, among nine CHD genes, CHD6 and CHD7 had the highest frequency of genetic gain/amplification, whereas CHD1 and CHD3 were most commonly deleted in a spectrum of human cancers." (PMID 28649742, 2017). "From the cross-cancer alteration analysis under the simultaneous query of MYC, NOLC1, DHX33, and CHD7, a large number of cancers possess alterations in these genes." (PMID 27198694, 2016). "In endometrial cancer, CHD7 modulates cancer-related pathways which have a negative impact on patient survival." (PMID 33869187, 2021).
genetic disorder (13 papers, 2009 to 2026). "It will be interesting to test if the paracrine signaling ligands supplementation can rescue CHD7 phenotypes in other organs, or alleviate phenotypes of genetic diseases caused by other genes." (PMID 36396635, 2022). "In humans, mutation of CHD7 can also cause a genetic disorder, CHARGE, which is characterized by severe defects in many cell types at birth (Vissers etal., 2004), implying that CHD7 is indeed involved in embryonic development." (PMID 23133442, 2012). "JBTS is a polygenic genetic disease with a poor prognosis, and the CHD7 gene might be related to JBTS." (PMID 37547106, 2023).
neurodevelopmental disorder (8 papers, 2012 to 2026). A behavioral and cognitive disorder with onset during the developmental period that involves impaired or aberrant development of intellectual, motor, or social functions. "AD patients exhibit hyperacetylation of histone 3 lysine residue 27 (H3K27) loci in the entorhinal cortex that extensively overlap with loci affected in patients with Kallman Syndrome, a neurodevelopmental disorder correlated with Chd7 mutations." (PMID 39125997, 2024). "CHD7 and CHD8 are implicated in neurodevelopmental disorders, which are characterized by aberrant expression of hundreds, if not thousands, of genes that collectively regulate common molecular pathways." (PMID 38474321, 2024).
infection (2 papers, 2016 to 2021). The state of being infected such as from the introduction of a foreign agent such as serum, vaccine, antigenic substance or organism. "Pathogenic variants of CHD7 were detected in nine neonates with infection, feeding difficulty, respiratory distress, and one or more malformations, which led to severe metabolic acidosis." (PMID 34733806, 2021). "Chd7 gene silencing decreased cell viability by half (0.51 ± 0.08 fold) 4 days after infection." (PMID 27955690, 2016).
psychiatric diseases (2 papers, 2016 to 2020). "Thus, the analysis of the effects of CHD7 mutations in human brain on psychiatric disorders regulated by NSPCs may be important in the future." (PMID 27955690, 2016).
CHD7 also shares sentences with these, for which no sentence is quoted: Anosmia (8 papers); Kabuki syndrome (7); Noonan syndrome (7); Hearing impairment (5); cardiovascular malformations (3); Down syndrome (3); hypoparathyroidism (3); lung squamous cell carcinoma (3); Micropenis (3); Usher syndrome (3); cervical cancer (2); cleft palate (2); Esophageal atresia (2); heart disease (2); Kartagener Syndrome (2); LEOPARD syndrome (2); liver cancer (2); non-syndromic hearing loss (2); Pendred syndrome (2); pituitary hormone deficiencies (2); renal coloboma syndrome (2); Waardenburg syndrome type 2 (2); Weaver syndrome (2); 3MC syndrome (1); acute lymphoblastic B-cell leukemia (1); Alagille syndrome (1); alpha 1-antitrypsin deficiency (1); amyotrophic lateral sclerosis (1); Anophthalmia (1); Ataxia (1).
A further 89 diseases each share a sentence with CHD7 in 1 paper.